PRDM9 (PR/SET domain 9)
Description:
Histone methyltransferase that sequentially mono-, di-, and tri-methylates both 'Lys-4' (H3K4) and 'Lys-36' (H3K36) of histone H3 to produce respectively trimethylated 'Lys-4' (H3K4me3) and trimethylated 'Lys-36' (H3K36me3) histone H3 and plays a key role in meiotic prophase by determining hotspot localization thereby promoting meiotic recombination. Can also methylate all four core histones with H3 being the best substrate and the most highly modified. Is also able, on one hand, to mono and di-methylate H4K20 and on other hand to trimethylate H3K9 with the di-methylated H3K9 as the best substrate (By similarity). During meiotic prophase, binds specific DNA sequences through its zinc finger domains thereby determining hotspot localization where it promotes local H3K4me3 and H3K36me3 enrichment on the same nucleosomes through its histone methyltransferase activity. Thereby promotes double-stranded breaks (DSB) formation, at this subset of PRDM9-binding sites, that initiates meiotic recombination for the proper meiotic progression (By similarity). During meiotic progression hotspot-bound PRDM9 interacts with several complexes; in early leptonema binds CDYL and EHMT2 followed by EWSR1 and CXXC1 by the end of leptonema. EWSR1 joins PRDM9 with the chromosomal axis through REC8 (By similarity). In this way, controls the DSB repair pathway, pairing of homologous chromosomes and sex body formation (By similarity). Moreover plays a central role in the transcriptional activation of genes during early meiotic prophase thanks to H3K4me3 and H3K36me3 enrichment that represents a specific tag for epigenetic transcriptional activation (By similarity). In addition performs automethylation (By similarity). Acetylation and phosphorylation of histone H3 attenuate or prevent histone H3 methylation (By similarity).
Synonyms: PFM6; ZNF899; KMT8B; Meisetz; MSBP3
Tractability: Small molecule: a structure with a bound ligand is known; a high-quality ligand is known. PROTAC: ubiquitination databases record sites on it; a small molecule that binds it is known.
Target class: PR domain; Protein methyltransferase; Writer; Epigenetic regulator
Chemical probes: MRK-740 (high quality)
Gene: Protein-coding gene on chromosome 5 (23,443,586 to 23,528,093, forward strand). Ensembl gene ENSG00000164256.
Subcellular location: Nucleus; Chromosome
Pathways (Reactome):
Chromatin organization: PKMTs methylate histone lysines
Reproduction: Meiotic recombination
Gene Ontology:
Molecular function: histone H3K36 methyltransferase activity; histone H3K36 trimethyltransferase activity; histone H3K4 methyltransferase activity; histone H3K4 trimethyltransferase activity; recombination hotspot binding; transcription cis-regulatory region binding; histone H3K9 trimethyltransferase activity; histone H4K20 monomethyltransferase activity; histone H4K20me methyltransferase activity; protein homodimerization activity; protein-lysine N-methyltransferase activity; histone methyltransferase activity; sequence-specific DNA binding; zinc ion binding
Biological process: meiotic gene conversion; positive regulation of reciprocal meiotic recombination; double-strand break repair involved in meiotic recombination; female gamete generation; homologous chromosome pairing at meiosis; male gamete generation; negative regulation of apoptotic process; positive regulation of fertilization; regulation of gene expression; chromatin remodeling; homologous recombination; meiosis I cell cycle process; regulation of DNA-templated transcription
Cellular component: chromosome; nucleoplasm; nucleus
Genetic constraint (gnomAD): Loss-of-function variants: 47 observed, 57.7 expected, observed/expected ratio (o/e) 0.81, 90% interval 0.64 to 1.04. The upper end of that interval is the gene's LOEUF score, 1.04, which puts it in group 4 of 6, group 1 being the genes least tolerant of losing a copy. Missense variants: 841 observed, 968.06 expected, observed/expected ratio (o/e) 0.87, 90% interval 0.82 to 0.92. Synonymous variants: 305 observed, 340.65 expected, observed/expected ratio (o/e) 0.9, 90% interval 0.81 to 0.98.
Homologues: Orthologues: chimpanzee PRDM9 (77% identical), mouse Zfp78 (18% identical). Paralogues in human: ZNF343 (32% identical), ZNF875 (30% identical), ZNF133 (29% identical), ZNF169 (28% identical), ZNF337 (26% identical), ZNF614 (21% identical), ZFP37 (20% identical), ZFP90 (20% identical), ZNF805 (20% identical), ZNF555 (20% identical), ZNF25 (19% identical), ZNF599 (19% identical), and 50 more.
Diseases named in the same sentence as PRDM9 in open-access papers:
PRDM9 is named in the same sentence as 208 diseases in open-access papers, as found by Europe PMC text mining. Sharing a sentence is not in itself a finding about the gene and the disease. The quoted sentences say what the papers report.
breast carcinoma (56 papers, 2012 to 2025). "Finally, piR-34736 (DQ596670), upregulated by 2-fold in TCGA HNSCCs and correlated to patient survival and PRDM9 mutation, was recently observed to be downregulated in breast cancers, with uncharacterized functional significance." (PMID 27323410, 2016). "The cell lines that express Prdm9 included the multiple myeloma cell line SKMM2 as well as the two breast cancer cell lines CAL851 and HCC1806." (PMID 31848333, 2019).
leukemia (35 papers, 2010 to 2024). A malignant (clonal) hematologic disorder, involving hematopoietic stem cells and characterized by the presence of primitive or atypical myeloid or lymphoid cells in the bone marrow and the blood. "For example, our RT-PCR validation demonstrates expression of a number of meiCT genes, including PRDM9, in lymphoma and leukaemia lines." (PMID 22918178, 2012).
Infertility (15 papers, 2009 to 2025). "In mice, PRDM9 is mainly expressed in the early stages of germ cell meiosis, and abnormal function of this gene can cause infertility in organisms." (PMID 38666830, 2024). "There are reports of a Bos indicus PRDM9 variant that, when introgressed into Holstein cattle, induced incompatibility of recombination hotspots and infertility in males but at the same time improved fertility of female hybrids." (PMID 35296233, 2022). "The Prdm9-/- mice showed accelerated oocyte loss from embryonic day 17.5 and infertility, which was similar to the ovarian phenotype of human POI." (PMID 34257419, 2021). "Relocation of meiotic DSBs to H3K4me3 at promoters and other functional genomic elements in the Prdm9 knockout B6 mice was suggested as a possible cause of infertility." (PMID 33910563, 2021). "Having confirmed that the introduction of a de novo Prdm9 allele rescues intersubspecific hybrid infertility, we next considered the impact of the de novo allele in a sterile hybrid generated from different species." (PMID 34491357, 2021). "Prdm9, the only known vertebrate hybrid-sterility gene, causes failure of meiotic chromosome synapsis and infertility in male hybrids that are the offspring of two mouse subspecies." (PMID 29537370, 2018). "The infertility of PWD x B6 F1 hybrid males is under the control of epistatic interaction between the Prdm9 gene on Chr 17 and X-linked Hstx2 genomic locus." (PMID 27104744, 2016). "Loss of PRDM9 function causes infertility in male mice as sperm arrest in meiotic prophase." (PMID 29702639, 2018). "Indeed, allelic variation at the DNA–binding positions of human PRDM9 zinc fingers show significant association with decreased risk of infertility." (PMID 19997497, 2009). "Furthermore, nonsynonymous SNPs in human PRDM9 are associated with infertility and azoospermia via meiotic arrest." (PMID 19997497, 2009). "Despite the persistence of these additional reproductive blocks, the data establish for the first time that PRDM9 is, and remains, a key but reversible part of the hybrid infertility between these two species." (PMID 34491357, 2021). "All previous studies of hybrid males carrying this Chr X and Prdm9 genotype combination have reported either infertility or extreme subfertility." (PMID 32817010, 2020). "The major phenotype of Prdm9−/− mice is an arrest of meiosis during the first meiotic division resulting in infertility." (PMID 31848333, 2019). "Knockout of the PRDM9 gene in both female and male mice leads to infertility because the deletion of the PRDM9 gene impairs the repair pathway for double-stranded DNA breaks, subsequently affecting the pairing of homologous chromosomes and causing impaired sex body formation." (PMID 38666830, 2024). "PRDM9-knockout mice are infertile due to the failure to properly repair DSBs." (PMID 24348265, 2013). "The same is true for the histone methyltransferase PRDM9 which leads to meiotic defects and thus infertility in mice, while in humans an individual identified with LOF variants in the PRDM9 gene was healthy and fertile." (PMID 40533538, 2025). "Recently, one third of PRDM9-dependent DSBs were reported within sequences that have at least some repetitive character, indicating that inappropriately high DSB levels in transposons and other repetitive elements may contribute to the infertility seen in some mouse hybrids." (PMID 29537370, 2018). "The proper allelic combination of Prdm9 and Hstx2 genes is necessary but not sufficient to govern HS completely because less than 10% instead of the expected 25% of (PWD x B6) x B6 male backcross progeny replicated the infertility of male PB6F1 hybrids." (PMID 29537370, 2018).
ovarian carcinoma (14 papers, 2012 to 2023). A malignant neoplasm originating from the surface ovarian epithelium. "For example, PRDM9 exhibits a significant mean up regulation in the ovarian cancer microarray sets used; however, it is not significantly up regulated in all the individual cancer samples tested, despite the significant mean elevation." (PMID 22918178, 2012).
glioblastoma (10 papers, 2015 to 2025). The most malignant astrocytic tumor (WHO grade IV). "Our data thus far suggest that PRDM9 is a vulnerability in drug-tolerant persister cells in glioblastoma." (PMID 41397959, 2025). "Taken together, these results support a model in which PRDM9 epigenetically regulates cholesterol biosynthesis necessary for the survival of glioblastoma persister cells." (PMID 41397959, 2025). "PRDM9 inhibition, combined with chemotherapy, results in strong anti-cancer efficacy in preclinical glioblastoma models, significantly enhancing the magnitude and duration of the antitumor response by eliminating persisters." (PMID 41397959, 2025). "Here, using brain-permeable microtubule-targeting agents we show that glioblastoma persister cells rely on the histone methyltransferase PRDM9 for survival." (PMID 41397959, 2025). "Further, our findings on the molecular and cellular functions of PRDM9 in glioblastoma expand the understanding of cancer-testis genes role in cancer." (PMID 41397959, 2025). "Nevertheless, in all models, cholesterol supplementation rescued the anti-persister effects of the PRDM9 inhibitor MRK-740, supporting a broader role for PRDM9 in regulating cholesterol biosynthesis and persisters survival across glioblastoma models." (PMID 41397959, 2025). "Here, multi-omics analysis and experimental approaches show that the germ-cell-specific H3K4 methyltransferase PRDM9 promotes metabolic rewiring in glioblastoma stem cells." (PMID 41397959, 2025). "In pursuit of optimising the outcomes of MTA chemotherapy, we show that PRDM9’s methyltransferase activity is critical for the survival of glioblastoma persister cells." (PMID 41397959, 2025). "Through histone proteomic, transcriptomic, lipidomic, and ChIP-sequencing studies combined with CRISPR knockout and phenotypic drug screen, we identify that chemotherapy-induced PRDM9 upregulation promotes metabolic rewiring in glioblastoma stem cells, leading to chemotherapy tolerance." (PMID 41397959, 2025). "Moreover, inhibiting PRDM9 in combination with brain-permeable MTAs results in strong anti-glioblastoma efficacy and significantly reduces the population of persister cells, the main reason for tumour recurrence." (PMID 41397959, 2025). "Together, these findings suggest that while PRDM9 is not an essential gene in glioblastoma, its expression increases in mitotically arrested cells and the development of a drug-tolerant state during chemotherapy is contingent on this methyltransferase." (PMID 41397959, 2025). "We found that PRDM9 expression was the most upregulated among H3K4 methyltransferases in persister cells, increased in a time-dependent manner following CMPD1 treatment and across six genetically diverse glioblastoma cell lines." (PMID 41397959, 2025). "We found that PRDM9 is non-essential enzyme in glioblastoma cells, and its inhibition leads to reversible cytostatic effects." (PMID 41397959, 2025). "Together, these findings suggest that early PRDM9-dependent H3K4me3 is critical for the survival of persister cells, whereas the subsequent removal of this mark - either through demethylation by KDM5 or histone cleavage by CTSL1 - is not a vulnerability of glioblastoma persister cells." (PMID 41397959, 2025).
sterility (10 papers, 2009 to 2022). "We found disrupted MSCI in reciprocal subfertile hybrids, consistent with Prdm9-associated sterility in both F1 hybrids." (PMID 34864964, 2022). "In human, a handful of PRDM9 SNPs have been shown to be associated with azoospermia and sterility as well." (PMID 24634223, 2014). "Several lines of evidence implicate the known sterility gene Prdm9 as the underlying causative gene." (PMID 24586194, 2014). "The restrictive expression of PRDM9 in testis and its association with sterility make this protein a desirable target for male contraceptive design." (PMID 24634223, 2014). "The peak of the QTL on chromosome 17 is coincident with the sterility gene Prdm9 and overexpression is caused by heterozygosity at this locus, consistent with maximal sterility effects in individuals heterozygous at Prdm9." (PMID 24586194, 2014). "Targeted PRDM9 knockout in the mouse causes sterility in both sexes due to a block in meiosis I in both the male and female germ line." (PMID 20041164, 2009). "Recent work indicates that allelic incompatibility in the mouse PRDM9 (Meisetz) gene can cause hybrid male sterility, contributing to genetic isolation and potentially speciation." (PMID 20041164, 2009). "In addition to allelic variation, the outcome of Prdm9-associated sterility is likely to be variable across cells within an individual." (PMID 34864964, 2022). "In human, several PRDM9 SNPs have been implicated in sterility as well." (PMID 24634223, 2014). "That only Hst1s/Hstws leads to sterility points to dosage-sensitivity as well as to deleterious interactions between some variants at PRDM9, as could happen, for example, if PRDM9 forms a homodimer." (PMID 22162947, 2011). "Thus, despite both reciprocal hybrids having identical Prdm9 genotypes (msc1/dom3), ♀musCZII × ♂domWSB produce some sperm with normal morphology, suggesting that other loci must modulate Prdm9-associated sterility in this cross." (PMID 34864964, 2022). "Therefore, the dominant-negative interaction(s) of the Prdm9B6 allele contributing to sterility in the (PWD×B6)F1 hybrid is most likely not a consequence of a change in the Prdm9 transcript level." (PMID 23133405, 2012). "Under this model, mismatched Prdm9-satellite DNA configurations would be predicted to result in sterility only in hybrid males, but not in hybrid females." (PMID 19997497, 2009).
Azoospermia (7 papers, 2009 to 2025). Absence of any measurable level of sperm,whereby spermatozoa cannot be observed even after centrifugation of the semen pellet. "In human, two SNPs, C614T in exon 6 and T1086C in exon 9, in PRDM9 were found to occur more frequently in Japanese patients with azoospermia caused by meiotic arrest than in the healthy control group." (PMID 24634223, 2014). "Mice lacking PRDM9 are sterile due to gametogenic failure and two studies have identified single nucleotide polymorphisms in PRDM9 that may be linked to azoospermia in humans." (PMID 27129774, 2016). "ZCWPW1 is a reader of dual histone methylation, specific for obstructive azoospermia patient PRDM9-catalyzed histone marks H3K4me3 and H3K36me3, and maintaining H3K9ac level around recombination hotspots." (PMID 38310235, 2024). "Intriguingly, in both studies, the effect on ameliorating azoospermia or oligospermia was manifest even in the heterozygous condition, suggesting that PRDM9's effect is semi-dominant (consistent with results of hybrid sterility seen in mouse Prdm9)." (PMID 19997497, 2009).
head and neck squamous cell carcinoma (7 papers, 2017 to 2025). A squamous cell carcinoma that arises from any of the following anatomic sites: lip and oral cavity, nasal cavity, paranasal sinuses, pharynx, larynx, and salivary glands. "Mutations in PRDM9 have yet to be correlated with some solid tumors, such as head and neck squamous cell carcinoma and bladder cancer." (PMID 36982660, 2023). "PRDM9 is recurrently mutated in head and neck squamous cell carcinoma, and an excess of rare PRDM9 alleles has been reported in aneuploid and infant B-cell precursor acute lymphoblastic leukemia patients." (PMID 35251135, 2022).
bladder cancer (6 papers, 2015 to 2023). "Through integrative analysis, we identified six HMT genes (PRDM9,ASH1L,SETD3,SETD5,WHSC1L1, and KMT2D) that may play a key role in the development and progression of bladder cancer." (PMID 30984543, 2019).
acute lymphoblastic leukemia (5 papers, 2015 to 2024). Leukemia with an acute onset, characterized by the presence of lymphoblasts in the bone marrow and the peripheral blood. "This opens up the possibility to investigate PRDM9 allelic diversity as a risk factor in patients with acute lymphoblastic leukemia and other diseases." (PMID 39114444, 2024). "Additionally, certain genetic variants of PRDM9 are found more frequently in specific patient populations, such as those who develop B-cell precursor acute lymphoblastic leukemia." (PMID 39114444, 2024). "Moreover, some rare PRDM9 variants have been linked to the development of acute lymphoblastic leukaemia in children, but PRDM9’s role in this disease is unclear." (PMID 30161134, 2018). "Rare PRDM9 allelic forms have been associated with childhood acute lymphoblastic leukaemia." (PMID 26186006, 2015). "Later, sequencing data revealed a substantial excess of rare allelic forms of PRDM9 in a cohort of parents with children affected from B-cell precursor acute lymphoblastic leukemia (B-ALL)." (PMID 32290321, 2020). "Excess rare PRDM9 allelic forms were found in B-cell precursor acute lymphoblastic leukemia (B-ALL) in children, which might influence genomic instability leading to aneuploidies formation related to childhood leukemogenesis." (PMID 34201935, 2021).
male infertility (5 papers, 2016 to 2024). The inability of the male to effect fertilization of an ovum after a specified period of unprotected intercourse. "During meiosis, in heterozygous males, the indicine PRDM9 variant may induce incompatibility of recombination hotspots and male infertility." (PMID 31462216, 2019). "Hence, haplotype #9, which was associated for sires with a negative score for male fertility, was also associated with the indicus-like PRDM9, suggesting that it drives male infertility as in Bos taurus–indicus hybrids." (PMID 31462216, 2019). "Low expression of the PRDM9 gene in the testes may be linked to male infertility in cattle." (PMID 38666830, 2024). "However, lower expression in sterile hybrids as compared to normal yaks suggests that PRDM9 gene might be associated with the male infertility of cattle-yaks." (PMID 27203728, 2016). "It was shown that Prdm9 knockout changes the distribution of DSBs across the genome inducing defective synapses and male infertility." (PMID 36776561, 2023). "These are not compatible with the recombination hotspots mediated by the taurine PRDM9 and thus drive meiosis in heterozygous individuals toward chromosomal instability and male infertility." (PMID 31462216, 2019).